STAT3 (signal transducer and activator of transcription 3)
Diseases named in the same sentence as STAT3 in open-access papers (continued):
Sharing a sentence is not in itself a finding about the gene and the disease.
lung carcinoma (continued). "STX-0119 also decreased the amount of STAT3 in the nuclear fraction as well as induced apoptosis of these lung cancer cell lines as evidenced by increases in apoptotic cells (Annexin V positive) and poly (ADP-ribose) polymerase (PARP) cleavage." (PMID 32257917, 2019). "STAT3 phosphorylation at Tyr705 by diverse upstream kinases, including cytokine receptors and tyrosine kinases, is a key step for STAT3 activation, which induces transcription of a wide array of genes that play critical roles in lung cancer pathogenesis." (PMID 30838170, 2019). "Meanwhile, recent studies also revealed that autophagy directly regulats JAK2/STAT3 signaling pathway in lung cancer cells." (PMID 30755242, 2019). "We further tested a predicted lead compound against lung cancer cells for possible STAT3 signaling inhibitory activity and it was found to have pronounced inhibition of the signaling cascade." (PMID 31847229, 2019). "In lung cancer cells resveratrol treatment decreases the activity of STAT3 and inhibits lung cancer progression by suppressing the pro-tumor activation of TAMs." (PMID 31035454, 2019). "Our results reveal that MVP inhibited lung cancer growth by suppression of STAT3 signal pathway, which is regulated by JAK2 and RAF-MEK-ERK pathways." (PMID 31092229, 2019). "The expression of miR-218 was found significantly downregulated in lung cancer tissues and it acted as a tumor suppressor in lung cancer by targeting IL-6/STAT3 and negatively correlated with poor prognosis." (PMID 31164163, 2019). "This study highlighted that LDOC1 acts as a novel native negative regulator of JAK2 and STAT3 in lung cancer." (PMID 30634502, 2019). "CAFs have also been shown to enhance the metastatic potential of lung cancers via IL-6/STAT3 signalling pathways." (PMID 31878245, 2019). "Because there was no change in the expression of HER2 in A549shG9a, we concluded that STAT3 was a potential therapeutic target against lung cancers with EGFR-TKI resistance that was superior to G9a." (PMID 31619200, 2019). "In conclusion, we demonstrated the STAT3-G9a-HER3 axis in lung cancer that evades EGFR-TKI therapies." (PMID 31619200, 2019). "Here we sought to understand the role of the epithelial STAT3 pathway in the development of K-ras mutant lung cancer." (PMID 30389925, 2018). "On the other hand, the report by Zhou and colleagues demonstrated that the role of STAT3 signaling in lung cancer pathogenesis is contextually dependent on the stage of tumorigenesis with STAT3 exhibiting contrasting roles in tumor initiation and progression." (PMID 30389925, 2018). "All in all, our findings demonstrate a critical sex-differential role for epithelial STAT3 signaling in the pathogenesis of K-ras mutant lung cancer." (PMID 30389925, 2018). "Our results showed that the combination of FZKA treatment with STAT3 knock-down increased the activities of both caspase-3 and caspase-9 in lung cancer cells, compared to FZKA alone." (PMID 30046347, 2018). "Our present study further sheds light on the role of STAT3 signaling in K-ras mutant lung cancer pathogenesis by highlighting stark sex disparity in this process and showing, in contrast, attenuated tumorigenesis in female mice with Stat3 deletion." (PMID 30389925, 2018). "It has also been found that curcumin treatment suppressed STAT3 phosphorylation and reduced the proliferative capacity of lung adenocarcinoma-derived H441 cells, indicating STAT3 as a potential target by curcumin in lung cancer." (PMID 29456509, 2018). "Knockdown of GPRC5A correlates with STAT3 activation in cancers such as lung cancer and head and neck squamous cell carcinoma (HNSCC), pointing to a tumor suppressive role for GPRC5A." (PMID 30417009, 2018). "In a previous study, it was shown that MEK inhibition triggers STAT3 signaling via IL‐6 in lung cancer." (PMID 29896883, 2018).
lung carcinoma (continued). "Aberrant activation of STAT3 has been identified in various human cancers, and correlates with poor prognosis in gastric, breast and lung cancer." (PMID 30417009, 2018). "The JAK/STAT3 pathway plays an important role in lung cancer for its close link with proliferation, metastasis and prognosis." (PMID 29552286, 2018). "We demonstrated the role of transcription factor Stat3, suggesting that inactivation of Stat3 was involved in the β-elemene inhibition of lung cancer growth." (PMID 30209296, 2018). "The FGFR4-388Arg variant has been reported to promote the activation of pathways related to cancer, such as the STAT3 signaling pathway in murine breast and lung cancer models." (PMID 29402970, 2018). "In this study, we found that the lower autophagy in lung cancer cells, the more obvious phosphorylation of STAT3; this coincides with previous reports, so we conclude that microRNA‐3127‐5p suppress autophagy activating STAT3 phosphorylation." (PMID 29726585, 2018). "Our results show that FZKA decoction promotes lung cancer cell apoptosis through STAT3/Bcl-2/caspase-3 signaling pathways." (PMID 30046347, 2018). "To clarify the important role of STAT3 in the apoptosis process of FZKA on lung cancer cells, we decreased the expression of STAT3 by STAT3 siRNA transfection." (PMID 30046347, 2018). "We also examined the ability of OP-D to modulate STAT3 activation in human lung cancer cell lines other than A549." (PMID 30413072, 2018). "On the other hand, it was also shown that the IL‐6/JAK/STAT3 signaling pathway‐mediated PD‐L1 increase in lung cancer cells was via activation of EGFR‐tyrosine kinase." (PMID 28865178, 2018). "Of note, targeting studies using tamoxifen revealed a crucial role for ER signaling in counteracting K-ras mutant lung cancer pathogenesis following Stat3 deletion in female mice." (PMID 30389925, 2018). "The downregulation of caveolin-1 expression can also inhibit STAT3 signaling pathways to block lung cancer cell metastasis." (PMID 30424755, 2018). "In this context, these findings strongly suggest that PLOD3 knockdown effectively suppresses the constitutive activation of STAT3 in lung cancer cells." (PMID 30442941, 2018). "Taken together, our study underscores a sex-differential role for epithelial STAT3 signaling in the development of K-ras mutant lung cancer." (PMID 30389925, 2018). "To gain insight into the potential signaling pathways involved in β-elemene-inhibited growth of lung cancer cells, we evaluated the effect of β-elemene on Stat3 signaling." (PMID 30209296, 2018). "AKT or STAT3 activation contributed to the effects of the MEK inhibitor in lung cancer cells with a KRASmutation62." (PMID 29844447, 2018). "STAT3 plays an important role in metastasis in different cancer models, including lung cancer, by participating in multiple steps of metastasis." (PMID 30442941, 2018). "Based on attractive anticancer activity of PSD-A against A549 lung cancer cells, we designed the study to further explore its effect on STAT3 activation." (PMID 29576846, 2018). "Recently, HHT has been shown to induce apoptosis and suppress STAT3 via IL-6/JAK1/STAT3 signal pathway in Gefitinib-resistant lung cancer cells." (PMID 29788973, 2018). "Generally, the biological functions of IL-6 are achieved via the Janus kinases/STAT3 (JAK/STAT3) pathway that is frequently presented in cancers including lung cancer." (PMID 29416638, 2018). "Collectively, TM4SF4-derived signaling pathways including GSK3β/β-catenin and JAK2(or FAK)/STAT3 appear to be focused on the secretion level of OPN and thus strengthen EMT-associated CSC-like properties in lung cancer cells." (PMID 29254164, 2017). "Skp2, a transcriptional target of STAT3, is a vital protein in lung cancer metastasis and proliferation." (PMID 29207614, 2017).
lung carcinoma (continued). "Our results revealed a strongly declined expression of oncogenes c‐myc and c‐kit, while STAT‐3 expression in contrary was increased in NK cells from lung cancer patients but was down‐regulated in NK cells from gastric, sigmoid, and colon cancer patients." (PMID 28695716, 2017). "Taken together, these findings revealed a novel mechanism that CAFs induced EMT and promoted metastasis of lung cancer cells through the IL-6/STAT3 signaling pathway." (PMID 29100297, 2017). "Some previous study indicated that IL-6/STAT3 signal was required for TGF-β-induced EMT process in lung cancer cells, and the crosstalk between the IL-6/STAT3 and TGF-β/p-SMAD3 signaling pathway did exist in certain conditions." (PMID 27992365, 2017). "Cav-1 controls proliferation of metastatic lung cancer cells by regulating STAT3 signaling, while STAT3 can promote directional cell migration by organizing the actin cytoskeleton." (PMID 29221162, 2017). "Drugs, like the antibiotic doxycycline, inhibit STAT3 in lung cancer cells at the cost of severe side effects in patients like nausea, vomiting and diarrhea, rash and sensitivity to sun." (PMID 29299146, 2017). "Our study highlights the importance of sustained Stat3 signaling, and its regulation by Rip4, in an autochthonous model of oncogenic Kras-driven lung cancer." (PMID 28574510, 2017). "Taken together, these results demonstrate that loss of ING5 enhances aggressiveness of lung cancer cells by promoting EMT via activation of EGFR/PI3K/Akt and IL-6/STAT3 signaling pathways." (PMID 28903339, 2017). "Treatment with SB-431542 (10 μM), JSI-124 (0.2 μM), or SB-431542 (5 μM) + JSI-124 (0.1 μM) inhibited the expression of JAK2, STAT3, survivin and c-myc in lung cancer cells in normal medium and MF-CM, based on RT-PCR measurements and by Western Blots." (PMID 28819126, 2017). "In vitro, highly-metastatic lung cancer H1650-M3 cells displayed electrotaxis in a voltage-dependent manner, which was controlled by Cav-1-mediated STAT3 activation." (PMID 29221162, 2017). "In this meta-analysis of eight studies, we found that p-STAT3 was overexpressed in lung cancer patients with poorer overall survival." (PMID 28797050, 2017). "It has been shown that targeting JAK/STAT3 with inhibitors results in downregulating self-renewal capability of lung cancer stem cells and displays reduced resistance to multiple cancer drugs." (PMID 28830450, 2017). "Another strategy was to inhibit JAK2 or STAT3 activation by pretreating lung cancer cells with JAK2 specific inhibitor AG490 (100 μM) or STAT3 specific inhibitor Stattic (7.5 μM) for 24 h, then cultured with CAF-CM." (PMID 29100297, 2017). "A previous study demonstrated that Skp2 is a target of STAT3, and our previous work showed that Skp2 is dissociated from Skp1 and underwent proteolysis in lung cancer cells treated with 6-OAP." (PMID 27835873, 2017). "Seven studies with 822 patients were included in the meta-analysis of the relation between p-STAT3 overexpression and differentiation in lung cancer patients." (PMID 28797050, 2017). "The mechanism study showed that IL-6/STAT3 signaling pathway mediated the enhanced effect of CAFs on lung cancer cell metastasis." (PMID 29100297, 2017). "Recently, solamargine, a steroidal alkaloid glycoside extracted from the Chinese medicinal herb Solanum nigrum L. was shown to induce p38 phosphorylation and STAT3 dephosphorylation in lung cancer cells that can be blocked by SB203580." (PMID 28418923, 2017). "Constitutive activation of Stat3 had been confirmed to inhibit apoptosis and promote migration in various tumors, including lung cancer." (PMID 28743280, 2017). "Consistent with the reported effect of IL-6 on MUC1 overexpression in breast and lung cancer cells, exposure of AsPC-1 cells to IL-6 led to parallel increases in STAT3 phosphorylation and the expression of MUC1-C, and, to a lesser extent, ILK." (PMID 28692035, 2017).
lung carcinoma (continued). "p-STAT3 overexpression has significant correlation with poorer overall survival of lung cancer patients, as well as with more advanced TNM stages and lymph node metastasis." (PMID 28797050, 2017). "Our data supports that polyI:C (its analogue, Hiltonol) is a promising adjuvant in combination with anti-IL6 antibody and/or JAK2/STAT3 inhibitors, for lung cancer immunotherapy." (PMID 28427199, 2017). "Reduced RIP4 expression in human lung cancer cells enhanced STAT3 signaling whereas the opposite was true upon overexpression of RIP4, in a kinase activity-independent manner." (PMID 28574510, 2017). "CUR has been determined to suppress the tumor sphere formation capacity in lung cancer H460 cells by suppressing the JAK2/STAT3 signaling pathway." (PMID 28611316, 2017). "6-OAP inhibited tumor growth in SCID mice intravenously injected with lung cancer cells, and downregulated both STAT3 and Skp2 in tumor samples." (PMID 27835873, 2017). "Our study, both in vitro and in vivo, demonstrated that CAFs activated IL-6/STAT3 signaling pathway, leading to the enhanced metastasis potential of lung cancer." (PMID 29100297, 2017). "Overexpressing miR-218 in lung cancer reduced STAT3 signaling when tested both in vitro and in vivo." (PMID 28830450, 2017). "The mechanistic study demonstrates that IL-6/STAT3 signaling pathway mediates the enhanced effect of CAFs on lung cancer cells metastasis potential." (PMID 29100297, 2017). "Overall, these findings demonstrate that PROS exerts antiangiogenic and apoptotic effects via inhibition of STAT3/VEGF/CDK2 axis signaling as a potent anticancer agent for lung cancer treatment." (PMID 29254203, 2017). "Taken together; ALT induces oxidative stress-dependent apoptosis, inhibits STAT3 activation and augments doxorubicin toxicity in A549 lung cancer cells." (PMID 28740138, 2017). "IL-11 facilitated lung cancer cell chemoresistance to cisplatin via the IL-11R/STAT3 signaling pathway by promoting activation of the anti-apoptotic proteins Bcl-2 and Survivin in lung adenocarcinoma." (PMID 29100303, 2017). "Certain lymphomas and lung cancers have been reported to drive PD-L1 expression through the upregulation of the signal transducer and activator of transcription 3 (STAT3) and lymphoma kinase (ALK) signaling resistance." (PMID 28878676, 2017). "In intrahepatic cholangiocarcinoma STAT3 overexpression negatively correlates with the outcome of the patients, and in breast and lung cancer STAT3 has a key role in metastatic processes." (PMID 28903416, 2017). "Eight of these studies were analyzed to determine the correlation of p-STAT3 overexpression with the overall survival of lung cancer patients." (PMID 28797050, 2017). "In selected lung cancer cell lines, persistently activated or tyrosine-phosphorylated STAT3 is partially due to IL-6 induction, and IL-6/p-STAT3 pathway activation is confirmed to be critical for lung cancer progression." (PMID 27992365, 2017). "After multiple-testing correction, 112 SNPs in eight genes (ATR, EGFR, MET, PIK3R1, PIK3R3, PTPN2, STAT3, and STAT5A) remained significantly associated with lung cancer risk with FDR <0.20." (PMID 28400551, 2017). "When cultured with CAF-CM, both p-JAK2 and p-STAT3 expression in lung cancer cells were increased, and total STAT3 expression remained unchanged." (PMID 29100297, 2017). "Taken together, these data suggest that miR-218 modulated lung cancer cell phenotype through negatively regulating the STAT3 signaling pathway." (PMID 28830450, 2017). "Overall, these findings suggest that PROS exerts antiangiogenic and apoptotic effects via inhibition of STAT3/ VEGF/ CDK2 axis signaling as a potent anticancer agent for lung cancer treatment." (PMID 29254203, 2017). "We performed a systematic review and meta-analysis to explore the correlation between p-STAT3 overexpression and prognosis in lung cancer patients." (PMID 28797050, 2017).
lung carcinoma (continued). "Down-regulation of CCL2 expression by inhibiting phosphorylation of STAT3 led to the suppression of metastasis in breast and lung cancer." (PMID 28757590, 2017). "In the present study, we found that ALT primarily induces oxidative stress resulting in ER stress, mitochondrial dysfunction, and inhibition of STAT3 activation which ultimately lead to apoptotic cell death in A549 lung cancer cells." (PMID 28740138, 2017). "In summary, our data suggested that a low concentration (10 μM) of DT can block the phosphorylation of STAT3, the protein expression of Skp2, and the mRNA expression of STAT3 downstream genes to inhibit the migration ability of lung cancer cells." (PMID 29207614, 2017). "And repressed GPRC5A correlates with activated EGFR and STAT3 signaling in lung cancer, which explains dysregulated STAT3 induced by aberrantly activated EGFR in lung cancer." (PMID 28270740, 2017). "The wound healing results showed that the blockade of JAK2/STAT3 signaling effectively reversed the enhanced abilities of migration of lung cancer cells by CAF-CM." (PMID 29100297, 2017). "6-OAP formed hydrogen bonds with Ser611/Ser613/Arg609 at the SH2 domain of STAT3 and inhibited the constitutive and interleukin-6-induced phosphorylated STAT3 (pSTAT3), leading to inhibitory effects on lung cancer cells and suppression of Skp2 transcription." (PMID 27835873, 2017). "Our study demontrated that the TGF-β and IL-6/JAK2/STAT3 signaling pathways form a positive feedback signaling loop that mediated the interactions between MFs and lung cancer cells." (PMID 28819126, 2017). "Inappropriate activation of STAT3 is closely related to poor prognosis in many cancer patients, including lung cancer patients." (PMID 29254164, 2017). "Collectively, these findings indicated that CAFs induced EMT and enhanced the metastasis potential of lung cancer cells by activation of IL-6/STAT3 signaling pathway." (PMID 29100297, 2017). "Here, we demonstrate that specific Rig-G overexpression in lung cancer cells interferes with the expression of STAT3, miR21, and miR181b-1." (PMID 27602766, 2016). "For example, p-STAT3 expression was detected in patients with gastric cancer, esophageal cancer, lung cancer, renal cell cancer, cervical cancer, prostate cancer, and colorectal cancer." (PMID 27504822, 2016). "To confirm that cytoplasmic K685-acetylated STAT3 was localized to mitochondria, we separated the mitochondrial fraction from the cytoplasm in cancer and adjacent normal tissue samples obtained from lung cancer patients." (PMID 28004755, 2016). "Both A549- and CL1-5-CM increased the phosphorylation of STAT3, and laricitrin decreased the lung cancer-induced activation of STAT3 in CD14+ monocytes." (PMID 27833081, 2016). "In the A549 lung cancer cell line, constitutively acetylated STAT3 localizes to mitochondria, where it maintains the mitochondrial membrane potential and ATP synthesis in an active state." (PMID 28004755, 2016). "It has been reported that IL-22 overexpression in lung cancer cells protects the cells from apoptosis by activating STAT3, Bcl-2, and Ccl-xL and inactivating ERK1/2." (PMID 27445423, 2016). "NF-κB and STAT3 play pivotal roles in various aspects of the tumorigenic process in several cancer entities, including colon, lung cancer, and hepatocellular carcinoma." (PMID 27602766, 2016). "In conclusion, the results of the present study show that Rig-G inhibits lung cancer cell growth via MiR21/PTEN/Akt and miR181b-1/CYLD-dependent inhibition of NF-κB, which is associated with decreased STAT3 activity." (PMID 27602766, 2016). "Niclosamide as an effective STAT3 inhibitor has shown to block effectively STAT3/Bcl2/Bcl-xl and to reduce the radioresistance in animal lung cancer xenografts." (PMID 27923354, 2016). "In this study, we report the significant expression of BDNF in NSCLC samples and show that BDNF stimulation increases the synthesis of BDNF itself through activation of STAT3 in lung cancer cells." (PMID 27456333, 2016).